ESR1 (estrogen receptor 1)
Diseases named in the same sentence as ESR1 in open-access papers (continued):
Sharing a sentence is not in itself a finding about the gene and the disease.
cervical carcinoma (92 papers, 1993 to 2026). A carcinoma arising from either the exocervical squamous epithelium or the endocervical glandular epithelium. "In cervical cancer, estrogen signaling persists despite the loss of epithelial estrogen receptor α (ERα) through stromal signaling, alternative ERα isoforms, ERβ, and non-classical receptors such as G protein-coupled estrogen receptor 1 (GPER1)." (PMID 41752059, 2026). "Loss of ESR1 expression has been shown to enhance cervical cancer invasion but how HPV (Human papillomavirus) might dysregulate the expression ER signaling genes will need further investigation." (PMID 38582811, 2024). "ESR1 (estrogen receptor 1) is the encoding gene for estrogen receptor-α (ER-α) and has been shown to play an important role in mediating the invasion and progression of cervical cancer with ER-α expression loss." (PMID 39206151, 2024). "Numerous cell line studies have demonstrated a clear link between estrogen receptor overexpression and decreased angiogenic stimulation and, ultimately, improved prognosis, and another pre-clinical study of cervical cancer cells determined that estrogen receptor-1 loss promoted cancer invasion." (PMID 35267430, 2022). "In addition, Kaplan-Meier plotter showed that high expression of AHR, CYP1A1, HSP90AA1, and HSP90AB1 and low expression of ESR1 were associated with a high hazard ratio for poor overall survival in cervical cancers." (PMID 34784845, 2021). "Studies revealed that the loss of ESR1 expression has a major role in cervical cancer progression." (PMID 26308848, 2015). "In HPV-associated cancer model mouse, estrogen and its receptor estrogen receptor 1 (ESR1) are considered to be essential for the development of cervical cancer." (PMID 33947962, 2021). "Then, Western blotting and Edu experiments were also performed to demonstrate that the downregulation of CCDC144NL-AS1 in cervical cancer cells inhibited the expression of ESR1 and increased cell proliferative ability." (PMID 33682613, 2021). "We also found that KD of WAPL in human cervical cancer cells reduced estrogen sensitivity and expression of ESR1 downstream genes, MYC and Cyclin D1." (PMID 33947962, 2021). "On the other hand, there was only one downregulated hub gene (ESR1) with low expression and poor prognosis in cervical cancer patients (P < 0.05)." (PMID 33682613, 2021). "In particular, AHR, CYP1A1 and ESR1 were identified as potential prognostic biomarkers and shown to be correlated with immune responses in cervical cancer." (PMID 34784845, 2021). "High expression of AHR, CYP1A1, HSP90AA1, and HSP90AB1 and low expression of ESR1 were negatively correlated with the prognoses of cervical cancer patients." (PMID 34784845, 2021). "Methylation of the ESR1 promoter correlated with tumor grade, while unmethylated ESR1 predicted for chemoradiation resistance in cervical carcinoma." (PMID 32536040, 2020). "A positive connection between dCK and ESR1 in cervical cancer was found using correlation analysis." (PMID 40263268, 2025). "However, cervical cancer-derived cell lines and later stage cervical cancer show low-level expression of ESR1." (PMID 33947962, 2021). "This confirmed that the expression of ESR1 enhanced the immunity of the tumor microenvironment of cervical cancer, which may explain its role in the favorable prognosis of patients." (PMID 34784845, 2021). "The rate of ESR1 and EDNRB mutation was 6 and 7% in cervical cancer." (PMID 32368784, 2020). "BRCA1, ESR1, PCNA, and FGFR2 have already been shown to be associated with cervical cancer." (PMID 30020984, 2018). "Methylation of ESR1 was also found in many cervical cancer patients." (PMID 26308848, 2015). "However, the prognostic properties of ESR1 in cervical cancer have been less studied." (PMID 39206151, 2024).
cervical carcinoma (continued). "Therefore, the lnc-CCDC170–4:1 and ESR1 may be an important factor for evaluating the prognosis of cervical cancer, and their specific mechanism of action in cervical cancer is also one of our main research directions in the future." (PMID 39206151, 2024). "The expressions of lnc-CCDC170–4:1, ESR1, lncRNA SRA, and CYP19A1 were validated in 26 cases of cervical cancer tissue and 30 cases of normal cervical tissue using qRT-PCR." (PMID 39206151, 2024). "In this study, we investigated the role of ESR1 and its corresponding lnc-CCDC170–4:1 in cervical cancer." (PMID 39206151, 2024). "In conclusion, the expression of lncRNA SRA and CYP19A1 is elevated in cervical cancer, while lnc-CCDC170–4:1 and ESR1 expression is decreased in cervical cancer." (PMID 39206151, 2024). "Cynaroside and Astragalin exert their cervical cancer inhibitory functions by regulating several signaling proteins (e.g., EGFR, STAT3, CCND1, IGFIR, ESR1)." (PMID 38003540, 2023). "In this study, we showed that the expression of CYP1A1, AIP, CYP1B1, ESR1, and MAF was significantly correlated with the level of T cell infiltration in cervical cancer." (PMID 34784845, 2021). "In our study, we found that ESR1 and EDNRB expression levels were lower in cervical cancer samples than in the normal samples." (PMID 32368784, 2020). "Then, the top 40 hub genes were conducted to evaluate the expression and prognostic values of cervical cancer and 7 upregulated (BUB1, CCNB1, CDK1, AURKB, KIF11, PBK, NUSAP1) and 1 downregulated (ESR1) hub genes were selected to have significant values as biomarkers." (PMID 33682613, 2021). "Generally, high expression of AHR, CYP1A1, HSP90AA1, and HSP90AB1 and low expression of ESR1 were not conducive to the prognosis of cervical cancer patients." (PMID 34784845, 2021). "Ten genes validated with the TCGA database, including five DMGs (ESR1, EPB41L3, EDNRB,ID4, PLAC), might be used as biomarkers and therapeutic targets in the precise diagnosis and treatment of cervical cancer." (PMID 32368784, 2020). "Notably, all eight genes that were frequently methylated in the HPV-transfected cell lines and cervical cancer cell lines (i.e. TP73, ESR1, RARβ, DAPK1, MGMT, CADM1, CDH13 and CHFR) overlapped with those found to be methylated in the cervical carcinoma specimens." (PMID 17971771, 2007). "In breast and cervix carcinoma cell lines, c-Myc depletion led to a down-regulation of CA12 but not ESR1." (PMID 31979064, 2020).
atherosclerosis (83 papers, 2007 to 2025). A disease characterized by the build-up of fatty material and calcium deposition in the arterial wall resulting in partial or complete occlusion of the arterial lumen. "We also observed the causal effect of miR-18a-5p via ESR1, which leads to atherosclerosis and infarction." (PMID 36140236, 2022). "Finally, relative to the regulation of ESR1 (ERα), it can control atherosclerotic calcification and smooth muscle cell osteogenic differentiation, mediates susceptibility to early atherosclerosis in male mice, and is directly involved in the regulation of cholesterol metabolism in macrophages." (PMID 35071356, 2021). "Alterations in ESR1 expression and its function affect the atheroprotective effects of circulating estrogen in insulinogenic atherosclerosis." (PMID 35669732, 2022). "A study suggests that diminished ESR1 expression in hematopoietic/myeloid cells promotes aspects of the metabolic syndrome and accelerates atherosclerosis in female mice." (PMID 27251057, 2016). "ESR1 activates specific target genes in vascular smooth muscle, inhibits smooth-muscle-cell migration, and it accelerates endothelial cell growth to produce atherosclerosis-protective effects." (PMID 39334763, 2024). "While an obvious connection between these genes, HT, atherosclerosis, and methylation changes at either CpG site in blood cells is not presently evident, prior studies have shown that 17β-estradiol can both induce and decrease methylation at CpG sites through ESR1-mediated mechanisms." (PMID 35850911, 2022). "When balancing HT risks and benefits in early postmenopausal women with CV risk factors such as diabetes and hypertension, ESR1 Pvull, NOS3 G894T and T-786C polymorphism analysis may be considered in relation to endothelial-mediated benefits, fundamental in atherosclerosis progression process." (PMID 25077953, 2014). "FOS, ESR1, MAPK8, and SP1 are important targets for anti-aging, anti-atherosclerosis, and anti-fatigue." (PMID 39334763, 2024). "The molecular mechanism analysis revealed that the active components of WGP have a positive influence on the four potentially important therapeutic targets of aging, atherosclerosis, or fatigue (i.e., FOS, ESR1, MAPK8, and SP1)." (PMID 39334763, 2024). "For example, ESR1 and ESR2, which are expressed in smooth vascular muscle cells, are usually hypomethylated in human atherosclerosis and folic acid deprivation is shown to play a role in endothelial dysfunction linked with cardiovascular disease and aging." (PMID 30279699, 2018). "Previous studies of vascular tissue samples revealed alterations in methylation of ALOX15, ESR1, ESR2, MCT3 and TFPI2 genes in patients with atherosclerosis." (PMID 25856389, 2015). "The top three core genes of WGP-atherosclerosis were FOS, ESR1, and MAPK8." (PMID 39334763, 2024). "Also, DNA hypermethylation has been observed in the estrogen receptor genes ESR1 and ESR2 of vascular smooth muscle which contributes to atherosclerosis." (PMID 25364756, 2014). "NBP can stably bind ALB, ESR1, EGFR, HSP90AA1, and other targets, and may play a role in neuroprotection for patients with DEACMP by modulating Lipid and atherosclerosis, IL-17 signaling pathway, MAPK signaling pathway, FoxO signaling pathway, PI3K/AKT signaling pathway." (PMID 37006490, 2023). "The top three WGP ingredients (quercetin, EGCG, and kaempferol) could bind stably to the top four core genes of aging, atherosclerosis, and fatigue (FOS, ESR1, MAPK8, and SP1), except that EGCG could not dock successfully with SP1." (PMID 39334763, 2024).
colorectal cancer (82 papers, 2008 to 2026). A primary or metastatic malignant neoplasm that affects the colon or rectum. "As the prognostic significance of ESR1 in an eight genes assessment model in liver cancer, and ER‐β expression in colorectal cancer and ESR2 polymorphisms in advanced gastric cancer." (PMID 32536040, 2020). "In colorectal cancer, concordance of KRAS mutations vary between 86.4% and 92%, estrogen receptor 1 (ESR1) mutation in metastatic breast cancer is concordant in 74.3% of patients and actionable EGFR in NSCLC was reported to be concordant in 79% of patients." (PMID 35741030, 2022). "The experimental evidence explains the cellular and molecular mechanisms of estrogen-mediated protection against colorectal tumorigenesis and suggests that ESR1 future challenges and potential avenues for colorectal cancer targeted therapy." (PMID 32883271, 2020). "Similar expression patterns were seen for ESR1, with highest expression in breast, ovarian, and uterine cancers, and lowest expression in colorectal cancers." (PMID 29973689, 2018). "We observed little support for an association of gene variants in hormone receptors (ESR1, ESR2, PGR) and active estrogen synthesizers (HSD17B1, HSD17B2, and HSD17B4) with colorectal cancer risk among postmenopausal women of European descent." (PMID 21627810, 2011). "Few candidate-gene studies have evaluated variation in hormone receptors (ESR1, ESR2, PGR) in relation to colorectal cancer risk." (PMID 21627810, 2011). "No mutated ESR1 was amplified in SW480 colorectal cancer cell DNA, which was used as a negative control." (PMID 29531247, 2018).
depression (81 papers, 2013 to 2025). "Specifically, Esr1 gene variants, which code for ERα, have been associated with increased risk of developing depression in women." (PMID 30863326, 2019). "Another study conducted in postmenopausal females found that the ESR1 454(-351) AG and 454(-351) AG + GG genotypes were related with lower risk of depression." (PMID 30544539, 2018). "Women carrying the AA alleles in the ESR1 polymorphism rs9340799 had an increased lifetime prevalence of major depression among postmenopausal female users of hormonal therapy." (PMID 30544539, 2018). "Also of note, ESR1 has been identified as a driver causal gene in an integrated genomic analysis of individuals with depression and/or PTSD, two conditions frequently comorbid with SI and highly genetically correlated with SI." (PMID 36940203, 2023). "However, a genetic association study identified a possible link between Esr1 polymorphisms and depression in men." (PMID 30863326, 2019). "Therefore, changes in ESR1 expression may regulate estrogen signaling and further influence the susceptibility of the body to depression." (PMID 36506595, 2022). "Among these core targets, SIRT1, HIF1A, ESR1, VEGFA, HSP90AA1 and PTGS2 are well documented to be associated with depression." (PMID 36496991, 2022). "A study of the relevant literature revealed that ESR1 serves as a key factor of depression, particularly in women." (PMID 35548356, 2022). "The six predominant targets (TNFα, ESR1, TLR4, PTGS2, MMP9 and NOS3) have been well documented to associate with depression." (PMID 35626632, 2022). "PPI network analysis showed that VEGFA, EGFR, CASP3, IL6, ESR1, and other targets have important implications in the treatment of depression with XPJYD." (PMID 34257681, 2021). "While there is no literature that shows the effect of anthraquinone and vanillic acid on ESR1, studies showed that it acts as an important factor of depression especially in women." (PMID 32182911, 2020). "The results of our study support the role of anthraquinone, kaempferol, and vanillic acid on MAOA, MAOB, and ESR1 in the etiology of depressive disorder." (PMID 32182911, 2020). "Part of the components of Si-ni San can bind to NOS2 and ESR1, which may play a role in improving depression combined with anxiety through these pathways." (PMID 39247617, 2024). "And ESR1, an estrogen receptor, was also found to be important in depression." (PMID 36339846, 2022). "Several studies have suggested that ESR1 has a role in depression." (PMID 30544539, 2018). "In addition, the ESR1 mRNA isoform profiles can change with disease state, for example in schizophrenia, bipolar disorder, and depression, where the canonical full-length form of ESR1 mRNA is reduced or becomes undetectable within the brain." (PMID 28617822, 2017). "Of note, considering that Esr1 functions may vary significantly depending on projection patterns and brain regions, it remains challenging to definitively determine which specific neuronal subpopulations contribute to depression." (PMID 41208898, 2025). "This study predicted that linalool, p-cymene, α-terpinene, terpinen-4-ol, and α-terpineol primarily contribute to CBEO’s anti-depressant effect, mainly via interactions with OPRM1, PTGS2, ESR1, SLC6A4, DRD2, and NR3C1, the six depression-related targets." (PMID 38567354, 2024). "Based on the network topology combined with the PPI analysis, we obtained that TCEF can regulate depression through five core targets, namely, ALB, AKT1, TNF, ESR1, and CTNNB1." (PMID 36506595, 2022). "UHPLC-Q-EOMS was employed to identify 59 major components of TCEF, and network pharmacology analysis was used to screen 48 active components of TCEF for treating depression, corresponding to 139 relevant targets, including ALB, AKT1, TNF, ESR1, and CTNNB1." (PMID 36506595, 2022).
depression (continued). "Studies have shown that AKT1, VEGFA, ESR1, IL6, and AR play an important role in the treatment of depression." (PMID 34257681, 2021). "In conclusion, the most important bioactive components—anthraquinone, kaempferol, and vanillic acid—can alleviate depression symptoms by regulating MAOA, MAOB, and ESR1." (PMID 32182911, 2020). "This perspective advocates for considering ESR1 and ESR2 genes in postnatal depression research." (PMID 39588356, 2024). "The node degrees of IL6, nitric oxide synthase 3 (NOS3), solute carrier family 6 member 4 (SLC6A4), estrogen receptor (ESR1), and tumor necrosis factor (TNF) were greater than 10, suggesting that these targets could play important roles in the effects of AL on depression." (PMID 36431060, 2022).